ATP6V1A (ATPase H+ transporting V1 subunit A)
Diseases named in the same sentence as ATP6V1A in open-access papers (continued):
Sharing a sentence is not in itself a finding about the gene and the disease.
Endometrium (1 paper, 2019). "Two of the somatic mutations COSM1177811 in RECK and COSM1036559 in ATP6V1A were observed in Endometrium." (PMID 31338326, 2019).
gastric adenocarcinoma (1 paper, 2017). "We found that the expression level of the ATP6V1A gene is significantly elevated in gastric adenocarcinomas in comparison to normal stomach tissues." (PMID 28592880, 2017).
hepatocellular carcinoma (1 paper, 2023). A malignant tumor that arises from hepatocytes. "In hepatocellular carcinoma cells, ATP9A was critical for regulating macropinocytosis via interaction with ATP6V1A resulting in plasma membrane cholesterol accumulation." (PMID 37686603, 2023).
liver cancer (1 paper, 2020). An epithelial or non-epithelial malignant neoplasm that arises from the liver. "Down-regulate the expression of ATP6V0C and ATP6V1A, which inhibits the activity of V-ATPase, reduces the invasiveness of liver cancer cells." (PMID 33194650, 2020).
neonatal encephalopathy (1 paper, 2024). "As ATP6V1A-related phenotypes are being better described, it is crucial to consider both sides of the spectrum and highlight that not only severe neonatal encephalopathy and DEE but also very mild non-progressive phenotypes are possible." (PMID 39336810, 2024).
Onset (1 paper, 2022). The age group in which disease manifestations appear. "Intriguingly, using a large-scale, multi-omics profiling approach, ATP6V1A (one of the STK11IP-interacting proteins) has recently been identified as a key regulator of the pathogenesis of sporadic late-onset Alzheimer’s disease." (PMID 35365663, 2022).
temporal lobe epilepsy (1 paper, 2024). A localization-related (focal) form of epilepsy characterized by recurrent seizures that arise from foci within the temporal lobe, most commonly from its mesial aspect. "Noteworthily, proteins such as ATP6V1A, DLAT, and HSP70 are expressed in the hippocampus of patients with temporal lobe epilepsy." (PMID 39360273, 2024).
triple-negative breast carcinoma (1 paper, 2021). An invasive breast carcinoma which is negative for expression of estrogen receptor (ER), progesterone receptor (PR), and human epidermal growth factor receptor 2 (HER2). "In triple-negative breast cancer, down-regulating SIRT1 levels decreases the expression of ATPase H+ transporting V1 subunit A (ATP6V1A), a particular subunit of the vacuolar-type H+ ATPase (V-ATPase)." (PMID 33390835, 2021).
tumor (11 papers, 2015 to 2025). "In the present study, we observed an overexpression of ATP6V1A in CRC tumor tissues, which had an adverse effect on prognosis." (PMID 31024853, 2019). "CLC3 promoted cell proliferation and tumor stemness via V-ATPase activity, particularly ATP6V1A." (PMID 41339331, 2025). "The high expression levels of RAB7A, PIK3C3, ATP6AP1, ATP6V1A, CCDC22, and NPC1 were significantly associated with lower tumor purity of patients with hematologic cancer LAML, while TMPRSS2, PIK3C3, ATP6AP1, and ATP6V1A expressions were obviously correlated with higher tumor purity of KICH patients." (PMID 35082790, 2021). "However, studies investigating the ATP6V1A expression in other tumor tissues are scarce." (PMID 31024853, 2019). "Through large-scale CRISPRi screening, we discovered genetic modifiers in GBM cells, including ARPC4, PI4KA, ATP6V1A, UBA1, and NDUFV1, that regulated the efficacy of CAR T cell-mediated tumor killing." (PMID 38561797, 2024). "Given the role of CLC3 in promoting chemoresistance, lysosomal function, and tumor stemness, targeting CLC3 or its downstream effectors, such as V-ATPase—especially ATP6V1A—may represent a promising therapeutic strategy." (PMID 41339331, 2025).
cancer (10 papers, 2017 to 2026). A tumor composed of atypical neoplastic, often pleomorphic cells that invade other tissues. "We further explored the impact of ATP6V1A ubiquitination on epithelial-mesenchymal transition (EMT) in cancer cells since the Wnt/β-catenin signaling pathway plays a role in regulating transcriptional changes during EMT." (PMID 38486234, 2024). "Furthermore, knockdown of ATP6V1A in cancer cell lines using shRNA inhibited cancer cell migration in mouse and human cell models." (PMID 38486234, 2024). "ACE2, RAB7A, PIK3C3, ATP6AP1, NPC1, and ATP6V1A had a negative association with the sensitivity of 16 anti-cancer drugs (P < 0.05)." (PMID 35082790, 2021). "ALO suppresses autophagic flux, disrupts lysosomal homeostasis, and induces lysosomal vacuolation in cancer cells by inhibiting the function of HSPA8, impairing chaperone-mediated autophagy (CMA)-mediated ATP6V1A degradation." (PMID 42318659, 2026). "We manipulated the expression of FBXO9 in HEK293T and cancer cells via gene overexpression and RNA interference to determine the implications of FBXO9-mediated ATP6V1A ubiquitination." (PMID 38486234, 2024). "To gain further insights, we generated cancer cell lines with inducible expression of V1A-23 aa (a peptide that inhibits ATP6V1A ubiquitination) by disrupting the interaction between FBXO9 and ATP6V1A." (PMID 38486234, 2024). "Furthermore, 62.5% of SARS-CoV-2-required genes containing ACE2, TMPRSS2, ATP6AP1, ATP6V1A, and CCDC22 exhibited a significant upregulation in UCEC relative to normal tissue, while only PIK3C3 showed an obvious downregulation in this cancer." (PMID 35082790, 2021).
infection (10 papers, 2012 to 2024). The state of being infected such as from the introduction of a foreign agent such as serum, vaccine, antigenic substance or organism. "Viral P protein in cell supernatants was first detected at 18 h post infection, with a considerable reduction in ATP6V1A-knocked-down cells compared with that in control cells." (PMID 33208464, 2021). "Trans-complementation with the interacting domain of ATP6V1A restores RABV infection as ATP6V1A did in knocked-down cells." (PMID 33208464, 2021). "The expression of P protein was primarily detected at 6 h post infection in the cell lysates and at 18 h post infection in the cell supernatants, and the expression level increased substantially over time in the cells overexpressing ATP6V1A." (PMID 33208464, 2021). "The results showed that the infectivity of ERA-eGFP dramatically decreased in ATP6V1A-knocked-down cells compared with that in control cells post infection by 29%, 61%, and 49% at 36, 48, and 60 h post infection, respectively." (PMID 33208464, 2021). "The results showed that knockdown of ATP6V1A decreased RABV replication in the supernatant of infected cells by 6-fold at 36 h post infection." (PMID 33208464, 2021). "Viral P protein expression in cell supernatants or lysates was also enhanced by 7-fold in cells overexpressing ATP6V1A at 36 h post infection, which was consistent with the observed enhanced virus growth." (PMID 33208464, 2021). "Moreover, compared to mock-infected cells, AIV infection significantly downregulated Rab5 gene expression at 36- and 48-hours post-infection, while significantly upregulating ATP6V1A gene expression at 24-, 36- and 48-hours post-infection." (PMID 39652582, 2024). "Strikingly, the P protein was almost undetectable at 36 h post infection in the culture supernatants of ATP6V1A-knocked-down cells but was clearly detectable in the culture supernatants of the control cells, indicating that the knockdown of ATP6V1A suppressed viral replication." (PMID 33208464, 2021). "The results showed that overexpression of ATP6V1A promoted the growth of ERA virus and increased the viral titers by 5-fold at 18 h post infection." (PMID 33208464, 2021). "Viral titration with cell supernatants showed that ATP6V1A knockdown decreased viral titers by 5.1-fold at 6 h post infection and decreased RABV replication in HEK293T cells at all later times post infection." (PMID 33208464, 2021). "The knockdown of ATP6V0C reduced infection-mediated cytotoxicity, but the knockdown of ATP6V1A did not." (PMID 22829766, 2012). "Similarly, at the 48 hour timepoint, pattern "MTB" includes 288 genes whose expression levels changed preferentially after infection with mycobacteria (e.g. CCL1, ATP6V1A, IL27RA), but only 33 of these genes are in the corresponding pattern at the 18 hour timepoint." (PMID 26586179, 2015).
neurodegenerative disease (4 papers, 2020 to 2025). A disorder of the central nervous system characterized by gradual and progressive loss of neural tissue and neurologic function. "ATP6V1A, V-type proton ATPase catalytic subunit A, participates in lysosomal pH acidification; altered v-ATPase has been implicated in numerous neurodegenerative diseases." (PMID 32295833, 2020). "Thus, dysregulation of Pgk1 and ATP6v1a represent a pathological loop linking energy deficits to lysosomal dysfunction, glial activation, and tau pathology, ultimately contributing to neurodegenerative disease progression." (PMID 40671812, 2025). "Thus, the present work identifies the novel axis “hypoxia-ATP6V1A-metabolic reprogramming-anti-aging” and offers further mechanistic insights into bone aging and additional potential intervention targets for metabolic and oxidative stress-related degenerative diseases." (PMID 41463574, 2025).
ATP6V1A also shares sentences with these, for which no sentence is quoted: colon cancer (3 papers); developmental and epileptic encephalopathy (3); developmental delays (3); Encephalopathy (3); neurodevelopmental disorder (2); acquired microcephaly (1); asthma (1); autism (1); Autoimmunity (1); Bardet-Biedl syndrome (1); calcium oxalate kidney stones (1); cone-rod dystrophy (1); COVID-19 (1); dementia (1); developmental disabilities (1); diabetes (1); epidermoid carcinoma (1); esophageal squamous cell carcinoma (1); gastric tumor (1); glioblastoma (1); glioma (1); hair loss (1); heart disease (1); hematologic cancer (1); Immunodeficiency (1); interstitial nephritis (1); Jaundice (1); lipodystrophy (1); liver disease (1); lymph node metastasis (1).
A further 19 diseases each share a sentence with ATP6V1A in 1 paper.